IAPP (islet amyloid polypeptide)
Diseases named in the same sentence as IAPP in open-access papers (continued):
Sharing a sentence is not in itself a finding about the gene and the disease.
type 2 diabetes (continued). "Amyloid self‐assembly of islet amyloid polypeptide (IAPP) is linked to pancreatic inflammation, β‐cell degeneration, and the pathogenesis of type 2 diabetes (T2D)." (PMID 31999880, 2020). "These include α-synuclein (α-Syn) in Parkinson’s disease (PD), amyloid beta (Aβ) and Tau in Alzheimer’s disease (AD), prion protein (PrP) in prion disease, and islet amyloid peptide (IAPP), also known as amylin, in type 2 diabetes mellitus (T2DM)." (PMID 33187056, 2020). "Enhanced IAPP production may contribute to islet amyloid formation in type 2 diabetes." (PMID 28980863, 2017). "In conclusion, IAPP targeting immunotherapy may have benefits in patients with type 2 diabetes." (PMID 27379014, 2016). "Human islet amyloid polypeptide (hIAPP), a 37-amino acid residue polypeptide, has the propensity to form the oligomers and fibrils which are thought to be toxic to the pancreatic islet β-cells and play the pathological role in the development of type II diabetes." (PMID 28074190, 2016). "The misfolding and aggregation of the 37-amino acid peptide, islet amyloid polypeptide (IAPP), is thought to be one of the main factors responsible for the β-cell defect that drives the pathogenesis of type 2 diabetes mellitus (T2DM)." (PMID 27531121, 2016). "As for type II diabetes, although the molecular mechanism of its pathogenesis remains elusive, there is also evident that the key pathological species are transient β-sheet-rich oligomers of IAPP, which therefore represent therapeutic targets for treatment of type II diabetes." (PMID 23755253, 2013). "Parenthetically, it may be mentioned that these species discrepancies have been utilized by a pharmaceutical company to make a non-fibrillogenic IAPP variant, used for treatment of type 1 and type 2 diabetes." (PMID 21486192, 2011). "We previously identified a small molecule, YX-I-1, which inhibits in vitro amyloid formation by islet amyloid polypeptide (IAPP), a peptide hormone whose amyloid formation is involved in type-2 diabetes." (PMID 39985130, 2025). "As aggregation of human islet amyloid polypeptide (hIAPP) is toxic to beta cells, we sought to determine whether activation of the fibrinolytic system can also reduce islet amyloid deposition and its cytotoxic effects, which are both observed in type 2 diabetes." (PMID 39245780, 2024). "We used islet amyloid polypeptide (IAPP), whose aggregation is observed in type 2 diabetes, as a model substrate." (PMID 40395301, 2023). "However, IAPP aggregates, related to type 2 diabetes mellitus (T2DM), are toxic not only for the pancreas, but also for the brain." (PMID 36793056, 2023). "Two monoclonal antibodies (mAbs) are reported that bind human islet amyloid polypeptide (hIAPP) protofibrils and inhibit their aggregation and toxicity to pancreatic islets in a mouse model of rapidly progressing type 2 diabetes mellitus (T2D)." (PMID 36257905, 2022). "Previously, we have elucidated the potential of type 2 diabetes mellitus (T2DM) in facilitating PD progression, involving aggregation of both alpha-synuclein (α-syn) and islet amyloid polypeptide in the pancreatic and brain tissues." (PMID 35255986, 2022). "In an in vitro acute injury study of human islets exposed to glucolipotoxicity, there was also some overlap with islets from humans with type 2 diabetes by RRHO analysis, but the overlap was weaker compared with IAPP overexpression in the current study." (PMID 34554282, 2022). "However, human IAPP (hIAPP) aggregates are toxic to β-cells and contribute to progressive β-cell dysfunction and death in type 2 diabetes (T2D) as well as in cultured and transplanted islets." (PMID 29474443, 2018). "Thus, based on the current consensus, the aim of our study was to determine if immunotherapy targeting IAPP could be used as a novel treatment strategy to prevent fibrillogenesis of and/or remove IAPP aggregates and improve glucose regulation in type 2 diabetes." (PMID 27379014, 2016).
type 2 diabetes (continued). "For instance, islet amyloid polypeptide (IAPP) chains are aggregated to form an one-dimensional fibril structure, and such IAPP fibril has been found in patients suffering from type II diabetes." (PMID 24551113, 2014). "Serum levels of BMP-4 increased progressively in rats transgenic for human islet amyloid polypeptide (HIP rats, a model of type 2 diabetes), resulting in a greater ability to induce BMP-dependent osteogenesis in calcifying vascular cells." (PMID 24170999, 2013). "Deposition of amyloid, derived from the polypeptide hormone islet amyloid polypeptide (IAPP; ‘amylin’) is the single most typical islet alteration in type 2 diabetes." (PMID 21486192, 2011). "Mouse IAPP does not form amyloid, but mice overexpressing human IAPP develop spontaneous type 2 diabetes." (PMID 37635876, 2023). "Altogether, IAPP and proinsulin may contribute to type 2 diabetes by activating the PERK pathway, and these studies highlight protein misfolding involved in type 2 diabetes." (PMID 35205066, 2022). "Winter and colleagues investigated the effects of non-sugar osmolytes on the fibrillation of the islet amyloid polypeptide (IAPP), which is implicated in Type 2 diabetes." (PMID 35883507, 2022). "Species with amyloidogenic IAPP, such as humans, non-human primates and cats, share vulnerability to type 2 diabetes, while those with non-amyloidogenic IAPP, such as mice and rats, do not." (PMID 34554282, 2022). "Increased expression of human IAPP, but not rodent IAPP, induced islet inflammation present in prediabetes and type 2 diabetes in humans." (PMID 34554282, 2022). "Type 2 Diabetes Mellitus (T2DM) is one of these protein misfolding disorders (PMDs) and involves human islet amyloid polypeptide (hIAPP) misfolding and accumulating in parts of the body, primarily in the pancreas, causing damage to islet cells and affecting glucose regulation." (PMID 35475576, 2022). "Human islet amyloid polypeptide (IAPP) is another acclaimed amyloid protein that can be triggered by many biological, environmental, and chemical factors into ß-sheets structured agglomerations and is also a distinctive mark of type 2 diabetes." (PMID 32962061, 2020). "Due to this difference in amino acid sequence of IAPP, islet amyloid deposition is detected in approximately 90% of patients with type 2 diabetes but not in rodent diabetes." (PMID 31447682, 2019). "The nanobody B10AP grafted with Gd(DOTA) shows detection towards amyloid fibers of islet amyloid polypeptide (IAPP) and fibers of transthyretin (TTR), which are involved in type 2 diabetes and polyneuropathy, respectively, and has great affinities with KD values in the 10-nM range in vitro." (PMID 30231587, 2018). "In a recent study, it is found that rat islet amyloid polypeptide (rIAPP) fibril does not induce the expression of type II diabetes despite the similarity between amino acid sequences of hIAPP and rIAPP except a single amino acid difference." (PMID 24551113, 2014). "Similarly, amyloid-β fibrils and islet amyloid polypeptide (IAPP) activate NLRP3, which contributes to Alzheimer’s disease and the progression of type 2 diabetes, respectively." (PMID 24367371, 2013). "The cross-association reaction between IAPP-GI (or nonfibrillar IAPP conformers) and Aβ may have some implications beyond its therapeutic potentials, and along with clinical and epidemiological evidences, provide a potential molecular link between AD and adult-onset diabetes." (PMID 21633500, 2011). "Islet amyloid polypeptide (IAPP) and pro-islet amyloid polypeptide (proIAPP) have been detected in cerebral and vascular Aβ deposits of AD patients, while Aβ reactivity is not present in islet amyloid extracts from patients with type 2 diabetes." (PMID 40305318, 2025). "Our data analysis has identified pathways and protein complexes that have been affected by toxic (though not lethal) levels of IAPP to Rin-5F cells and which may be involved in the pathogenesis of type II diabetes." (PMID 30419808, 2018).
type 2 diabetes (continued). "We study the effect of single point mutation of hIAPP20–29 constituting a hIAPP fibril on its molecular structure, since rat islet amyloid polypeptide (rIAPP) fibril does not induce any type II diabetes in a rat despite similarity between amino acid sequences of hIAPP20–29 and rIAPP." (PMID 24551113, 2014). "Similarly, our PRIOC mAbs were also able to bind synthetic oligomeric species of tau and islet amyloid polypeptide (IAPP) associated with tauopathies and type 2 diabetes, respectively, but not with their monomeric and fibrils counterparts (data not shown)." (PMID 25520699, 2014). "It is not understood why IAPP formsamyloid deposits in conjunction with type-2 diabetes." (PMID 18825272, 2008). "This suggests that IAPP concentration is not the critical factor contributing to its aggregation and proposes that other elements could play a determinant role in the amyloidogenic process and, accordingly, in the etiology of type II diabetes." (PMID 26576436, 2015).
diabetes (125 papers, 2005 to 2026). "DNA vaccination encoding IAPP induced diabetes in 25–33% of these mice, suggesting IAPP’s involvement in autoimmune diabetes development." (PMID 39859479, 2025). "Similar phenomena of membranes promoting α-helix formation followed by membrane damage have been observed for at least two other amyloidogenic proteins: α-synuclein, linked to Parkinson’s disease (Dikiy and D Eliezer, 2012) and IAPP, associated with diabetes." (PMID 40765848, 2025). "A previous study reported that 10-week circadian rhythm disturbances by 6 h advances of light-dark cycles every 3 days or constant light accelerated the loss of beta cell function in diabetes-prone human islet amyloid polypeptide transgenic rats." (PMID 39639385, 2024). "Progressive accumulation of IAPP in transgenic mice expressing human IAPP are susceptible to developing diabetes." (PMID 39676616, 2024). "Conversely, the amyloidogenic peptide deposit in the pancreatic islets of Langerhans associated with diabetes is known as islet amyloid polypeptide (IAPP), which is a peptide consisting of 37 amino acids." (PMID 37958889, 2023). "These AD amyloid plaques can also contain other amyloid proteins including islet amyloid polypeptide (IAPP), which is linked to diabetes mellitus." (PMID 39081980, 2023). "Here, we integrated kinetic investigations with structural studies to elucidate how the ubiquitous co-chaperonin prefoldin inhibits diabetes associated islet amyloid polypeptide (IAPP) fibril formation." (PMID 35501361, 2022). "Due to an amyloidogenic sequence, IAPP has the propensity to form oligomers and subsequently insoluble fibrils in species at risk to develop diabetes (cats, primates and humans)." (PMID 34069914, 2021). "T2DM, the most prevalent type of diabetes, is an islet amyloid polypeptide (IAPP)-associated pathology." (PMID 32265649, 2020). "The described findings highlight IAPP amyloidosis as one of the main causes of the beta cell dysfunction in the late stages of diabetes mellitus." (PMID 32724729, 2020). "The formation of amyloid oligomers and fibrils of the human islet amyloid polypeptide (hIAPP) has been linked with β- cell failure and death which causes the onset, progression, and comorbidities of diabetes." (PMID 31804529, 2019). "Here we focus on islet amyloid polypeptide (IAPP) mediated loss-of-insulin secreting cells in patients with diabetes." (PMID 29615609, 2018). "In our group we have demonstrated that the rat IAPP hexamers are diagnostic biomarkers of the onset and progression of diabetes mellitus and play a role as therapeutic targets." (PMID 29286329, 2017). "A number of other amyloidogenic polypeptides have been found to undergo lipid-induced aggregation coupled to membrane permeabilization, including islet amyloid polypeptide (IAPP) involved in diabetes and Aβ peptide associated with AD neuropathology." (PMID 28069058, 2017). "In support of this scenario, IAPP-deficient mice have been shown to develop a more severe form of alloxan-induced diabetes." (PMID 27379014, 2016). "According to major research, amylin or IAPP is a pancreatic peptide hormone naturally produced with insulin and appears to be involved in the cause of both main types of diabetes." (PMID 26582441, 2015). "The diabetes-associated human islet amyloid polypeptide (IAPP) is a 37-amino-acid peptide that forms fibrils in vitro and in vivo." (PMID 20495767, 2010). "IAPP (amylin) is a gene which has contrasting activities and has been associated with experimental diabetes in rodents." (PMID 15691381, 2005). "Diabetes is not only a risk factor that contributes to neurodegenerative disease, but also directly results in the accumulation of protein aggregates in the forms of IAPP (amylin) and advanced glycation end-products (AGEs)." (PMID 37443837, 2023).
diabetes (continued). "Previous studies have shown that islet amyloid polypeptide (IAPP) is a protein formed in patients with diabetes that causes activation of the NLRP3 inflammasome, triggering a series of inflammatory responses that produce mature IL-1β, a process also known as glucose metabolism." (PMID 35647057, 2022). "This provides compelling evidence associating IAPP aggregation with development of diabetes." (PMID 35455074, 2022). "Islet amyloid polypeptide (IAPP) deposition is associated with islet cell loss in diabetes." (PMID 33420039, 2021). "Recent evidence suggests that toxic IAPP aggregates and genetic mutations caused by the burden of excessive protein aggregation may be linked to β-cell dysfunction and diabetes." (PMID 34691567, 2021). "Collectively, these data suggest that IAPP and Aβ may interrelate by cross-seeding, offering a new potential explanation for the higher risk of AD in people affected by diabetes." (PMID 32503113, 2020). "IAPP has been identified due to its ability to aggregate in the amyloid deposits of pancreatic islets, which are seen primarily in association with type 2 diabetes in humans and diabetes in several other mammalian species, especially monkeys and cats." (PMID 32503113, 2020). "Several studies have implicated that IAPP aggregation can conversely aggravate the pathology of diabetes and accelerate the progression of diabetes, but whether IAPP deposits is a cause or a consequence of T2DM is still unclear." (PMID 32116510, 2020). "Diabetes is associated with islet amyloid polypeptide (IAPP) accumulation in the pancreatic islets." (PMID 32455946, 2020). "Corroborating the toxicity of these aggregates in diabetes, the IAPP allele S20G, which raises IAPP aggregation propensity, has been associated with premature onset diabetes and has accelerated the decline of endogenous insulin secretion when compared to non-S20G T2DM individuals." (PMID 32265649, 2020). "In heterozygous hIAPP+ mice with β cell–specific Atg7 deficiency (hIAPP+Atg7Δβcell mice), the accumulation of toxic oligomers, the loss of β-cells, and diabetes development is linked to autophagy disruption, and this is suggestive of a role for autophagy in IAPP toxicity." (PMID 32265649, 2020). "A study involving experimental disruption of the light-dark cycle in the form of either an advancing light period or a constant light period in diabetes-prone human islet amyloid polypeptide transgenic (HIP) rats accelerated the development of diabetes by increasing the loss of beta-cell function." (PMID 29385702, 2018). "More specifically, IAPP was shown to impair the blood–brain barrier; it was also seen to interact and co-deposit with amyloid beta peptide (Aß), and possibly with Tau, within the brain of Alzheimer's disease (AD) patients, thereby contributing to diabetes-associated dementia." (PMID 32265649, 2020). "In addition to IAPP and insulin with their important roles in T2D, genetics association studies have identified other T2D-related genes and corresponding variations across different populations with distinct diabetes risks." (PMID 25649462, 2015). "The link between glucotoxicity, lipotoxicity, and cholesterol with IAPP further provides insights into how metabolic alterations can exacerbate diabetes." (PMID 39859479, 2025). "IAPP oligomers play a crucial role in the pathogenesis of diabetes mellitus, particularly in the destruction of pancreatic beta cells and the dysfunction of insulin production." (PMID 39859479, 2025). "The aggregation of IAPP is a trigger of various metabolic disorders, particularly diabetes mellitus." (PMID 39859479, 2025). "They concluded that elevated plasma IAPP levels are observed in pancreatic cancer patients with diabetes." (PMID 39596226, 2024). "In vitro experiments have demonstrated that the characteristic deposit protein in diabetes, islet amyloid polypeptide (IAPP), interacts with alpha-synuclein, promoting its aggregation." (PMID 39655344, 2024).